FECH (ferrochelatase)
Description:
Catalyzes the ferrous insertion into protoporphyrin IX and participates in the terminal step in the heme biosynthetic pathway.
Synonyms: EPP; EPP1; FCE
Tractability: Small molecule: a structure with a bound ligand is known; a high-quality ligand is known; it has a high-quality binding pocket. Antibody: UniProt places it where antibodies can reach, with medium confidence. PROTAC: ubiquitination databases record sites on it; its protein half-life has been measured; a small molecule that binds it is known.
Target class: Enzyme; Lyase
Gene: Protein-coding gene on chromosome 18 (57,544,377 to 57,586,761, reverse strand). Ensembl gene ENSG00000066926.
Subcellular location: Mitochondrion inner membrane
Pathways (Reactome):
Metabolism: Heme biosynthesis
Metabolism of proteins: Mitochondrial protein degradation
Gene Ontology:
Molecular function: ferrochelatase activity; identical protein binding; protein binding; protein homodimerization activity; ferrous iron binding; iron ion binding
Biological process: heme B biosynthetic process; heme biosynthetic process; generation of precursor metabolites and energy; response to light stimulus; cellular response to dexamethasone stimulus; response to arsenic-containing substance; response to ethanol; response to insecticide; response to lead ion; response to metal ion; response to methylmercury; response to platinum ion; response to xenobiotic stimulus
Cellular component: ATP-binding cassette (ABC) transporter complex; mitochondrial membrane; mitochondrion; mitochondrial inner membrane
Genetic constraint (gnomAD): Loss-of-function variants: 34 observed, 52.71 expected, observed/expected ratio (o/e) 0.65, 90% interval 0.49 to 0.86. The upper end of that interval is the gene's LOEUF score, 0.86, which puts it in group 3 of 6, group 1 being the genes least tolerant of losing a copy. Missense variants: 407 observed, 508.01 expected, observed/expected ratio (o/e) 0.8, 90% interval 0.74 to 0.87. Synonymous variants: 169 observed, 195.18 expected, observed/expected ratio (o/e) 0.87, 90% interval 0.76 to 0.98.
Gene-disease validity (ClinGen):
ClinGen rates the evidence that FECH causes each of these diseases.
protoporphyria, erythropoietic, 1 (autosomal recessive): Definitive.
Homologues: Orthologues: chimpanzee FECH (99% identical), macaque FECH (94% identical), guinea pig FECH (90% identical), mouse Fech (88% identical), dog FECH (88% identical), rabbit FECH (87% identical), pig FECH (85% identical), rat Fech (85% identical), zebrafish fech (72% identical), tropical clawed frog fech (71% identical), Drosophila melanogaster FeCH (48% identical).
Diseases named in the same sentence as FECH in open-access papers:
FECH is named in the same sentence as 82 diseases in open-access papers, as found by Europe PMC text mining. Sharing a sentence is not in itself a finding about the gene and the disease. The quoted sentences say what the papers report.
erythropoietic protoporphyria (49 papers, 2008 to 2025). A rare congenital metabolic disorder characterized by an inborn error of porphyrin-heme biosynthesis. "Erythropoietic protoporphyria is an inherited disorder characterized by mutations in the FECH gene, which encodes the enzyme ferrous chelatase." (PMID 40604827, 2025). "Erythropoietic protoporphyria (EPP) is caused by loss-of-function mutations in ferrochelatase (FECH), leading to the accumulation of its substrate, protoporphyrin IX (PPIX)." (PMID 40540978, 2025). "Erythropoietic protoporphyria (EPP) is an autosomal recessive disorder of the heme biosynthesis pathway caused by pathogenic variants in FECH gene resulting in a decreased activity of ferrochelatase." (PMID 40007872, 2025). "Rarely, individuals with protoporphyria carry homozygous or compound heterozygous missense mutations in the FECH gene with an autosomal recessive inheritance pattern." (PMID 39011756, 2025). "Erythropoietic protoporphyria (EPP) (OMIM: 177000) is a cutaneous light sensitivity disorder that typically results from pathogenic variants in ferrochelatase (FECH), the last enzyme in heme biosynthesis." (PMID 40663422, 2025). "Erythropoietic protoporphyria (EPP) is caused by inactivating mutations in ferrochelatase (FECH), the enzyme that catalyzes the addition of iron to PPIX, the final step in heme biosynthesis." (PMID 40955661, 2025). "Mutations in the FECH gene, which lead to a reduction in FECH activity, result in a disorder known as erythropoietic protoporphyria (EPP)." (PMID 38928065, 2024). "Erythropoietic protoporphyria (EPP) is due to biallelic mutations in the FECH gene, which encodes for the enzyme responsible for the last step in heme biosynthesis, wherein PPIX is chelated with iron to form heme." (PMID 38256864, 2023). "Mutations causing a partial deficiency of FECH lead to erythropoietic protoporphyria (EPP) which is characterized by the accumulation of PPIX in the erythrocytes." (PMID 35923227, 2022). "Erythropoietic protoporphyria (EPP) is a rare autosomal recessive disorder caused by the moderate to severe deficiency (<20% activity) of ferrochelatase (FECH)." (PMID 35204362, 2022). "Erythropoietic protoporphyria (EPP) is caused by loss-of-function mutations in the ferrochelatase (FECH) gene, which in the last HB step inserts ferrous iron into protoporphyrin IX (PPIX) to form heme." (PMID 35923227, 2022). "Erythropoietic protoporphyria (EPP) is a cutaneous porphyria resulting from loss-of-function mutations in the ferrochelatase gene (FECH) with autosomal recessive Mendelian inheritance." (PMID 34988101, 2021). "Secondly, because a mutation of FECH induces protoporphyria and liver damage in BALB/c mice but is less severe in other strains including C57BL/6 J." (PMID 34900592, 2021). "Erythropoietic protoporphyria (EPP) is a genetic disorder caused by an abnormality in the ferrochelatase (FECH) gene involved in the heme synthetic pathway." (PMID 33400006, 2021). "Erythropoietic protoporphyria (EPP) is a rare disorder caused by reduced ferrochelatase activity and shows incomplete autosomal dominant inheritance." (PMID 31261042, 2019). "Erythropoietic protoporphyria (EPP) is caused by deficiency of ferrochelatase (FECH), which incorporates iron into protoporphyrin IX (PPIX) to form heme." (PMID 28093505, 2017). "Mutation, which causes bovine protoporphyria occurs in gene FECH that encodes ferrochelatase, that has been mapped to chromosome 24 (NCBI Gene ID: 281158)." (PMID 28458779, 2017). "The bovine protoporphyria or bovine ferrochelatase (OMIA 000836-9913) deficiency is inherited as recessive trait." (PMID 28458779, 2017). "Erythropoietic protoporphyria (EPP) is a disease associated with a diminished activity of ferrochelatase (FECH) (EC.4.99.1.1), the final enzyme of heme biosynthesis that catalyzes the conversion of protoporphyrin (PROTO IX) into heme." (PMID 24523661, 2014).
erythropoietic protoporphyria (continued). "Another intronic modifying polymorphism is found in the FECH gene responsible for erythropoietic protoporphyria, an autosomal dominant disorder characterized by incomplete penetrance." (PMID 23820649, 2013). "The hypomorphic C allele increases the penetrance of erythropoietic protoporphyria when it occurs in trans to a pathogenic FECH mutation." (PMID 23820649, 2013). "Ferrochelatase (FECH) activity is decreased in erythropoietic protoporphyria (EPP), causing increased production and excretion of protoporphyrin." (PMID 19787086, 2008). "The second type is further divided into classical erythropoietic protoporphyria (EPP) caused by ferrochelatase (FECH) loss-of-function mutation, and X-linked dominant protoporphyria (XLPP) caused by aminolavulinic acid synthetase 2 (ALAS2) gain-of-function mutation." (PMID 39965404, 2025). "FECH gene expression level has been associated with erythropoietic protoporphyria (EPP) in humans." (PMID 23766848, 2013). "Special attention should be devoted to EPP patients bearing FECH null mutations with recessive inherited disease, those belonging to families with more than one member with manifested disease or those with X linked protoporphyria." (PMID 19744342, 2009). "Similarly, the allele frequency of rs2272783 A > G in FECH, which is associated with erythropoietic protoporphyria, was nearly three times higher in the Vietnamese and East Asia populations than in the world population (28.10%, 32.57%, and 11.23%, respectively)." (PMID 33154511, 2020). "Erythropoietic protoporphyria (EPP) is a genetic disorder typically resulting from decreased ferrochelatase (FECH) activity, the last enzyme in heme biosynthesis." (PMID 40663422, 2025). "A bone marrow-homing heptapeptide was tested, among other targeting moieties, for the delivery of SSO to bone marrow in order to modulate ferrochelatase splicing in a mouse model of erythropoietic protoporphyria." (PMID 39451535, 2024). "Erythropoietic protoporphyria (EPP) is a genetic disorder stemming from reduced ferrochelatase expression, the final enzyme in the pathway of heme biosynthesis." (PMID 38256864, 2023). "Erythropoietic protoporphyria (EPP, MIM 177000) is a rare inherited disorder caused by the deficiency of ferrochelatase (FECH; EC4.99.1.1) that catalyzes the chelation of ferrous iron by protoporphyrin IX, in the last step of the heme biosynthetic pathway." (PMID 35309058, 2022). "Ferrochelatase (FECH) is the terminal enzyme in heme biosynthesis and plays vital roles in choroidal neovascularization, retinal neovascularization, and erythropoietic protoporphyria." (PMID 34861826, 2021). "Classical erythropoietic protoporphyria (EPP) is characterized by reduced activity of ferrochelatase (FECH), the last enzyme of the pathway." (PMID 34940556, 2021). "Perturbations in P. falciparum growth were observed in erythrocytes where ferrochelatase activity was reduced by at least 75% (in erythropoietic protoporphyria) or completely using a specific ferrochelatase inhibitor." (PMID 33014890, 2020). "Erythropoietic protoporphyria (EPP; OMIM # 177000) is a rare autosomal recessive disorder, that is caused by deficiency in the heme biosynthesis enzyme ferrochelatase (FECH, EC 4.99.1.1)." (PMID 32313951, 2020). "Mutations in the FECH gene cause erythropoietic protoporphyria (EPP; OMIM: #177000); the partial deficiency of FECH leads to the accumulation of free-PPIX in bone marrow, erythrocytes, plasma and finally in the liver." (PMID 24782769, 2014). "However, in any of the protoporphyrias, pathological variants in the ALAS2, CLPX or FECH genes lead to the accumulation of excess PPIX in the maturating erythroblasts in the bone marrow." (PMID 39011756, 2025). "Erythropoietic protoporphyria (EPP) is a rare genetic disorder caused (in the majority of patients) by a mutation in a gene encoding ferrochelatase (FECH), resulting in decreased levels of ferrochelatase enzymes involved in heme biosynthesis." (PMID 39451535, 2024).
erythropoietic protoporphyria (continued). "Erythropoietic protoporphyria (EPP), a rare inherited metabolic disease caused by heme perturbation, is characterized by the accumulation of metal-free protoporphyrin IX (PPIX) in erythroid cells due to a partial deficiency in ferrochelatase (FECH)." (PMID 39129919, 2024). "Most recently, it has been demonstrated that the deficiency of ferrochelatase (FETCH), a gene involved in the last step of heme production and responsible for the development of Erythropoietic protoporphyria, damaged both glycolysis and OXPHOS along with a decrease in mitochondrial fusion." (PMID 34573969, 2021). "Erythropoietic protoporphyria (EPP) is a hereditary disease due to a decreased activity of ferrochelatase (Fech) (EC.4.99.1.1), the last enzyme of heme pathway catalyzing the incorporation of ferrous iron (II) into protoporphyrin IX (PROTO IX) to synthetize heme." (PMID 25945334, 2015). "Erythropoietic protoporphyria (EPP) and X-linked protoporphyria (XLP) are inherited disorders resulting from defects in two different enzymes of the heme biosynthetic pathway, i.e., ferrochelatase (FECH) and delta-aminolevulinic acid synthase-2 (ALAS2), respectively." (PMID 35054318, 2022). "Regulation of FECH expression affects PPIX levels in various diseases, including protoporphyria and bladder cancer." (PMID 39682298, 2024). "Erythropoietic protoporphyria (EPP) is a rare disorder of heme biosynthesis hallmarked by early‐onset photosensitivity and mainly due to defective ferrochelatase activity leading to increased erythrocyte protoporphyrin IX (PPIX) levels." (PMID 34420239, 2022). "Partial deficiency of the last enzyme of the heme biosynthetic pathway, namely, ferrochelatase (FECH), is responsible for erythropoietic protoporphyria (EPP) in humans." (PMID 35309058, 2022). "Supporting this latter assertion, in the genetic disease erythropoietic protoporphyria (EPP), FECH activity is markedly reduced, but EPP patients infrequently present severe symptoms apart from skin photosensitivity." (PMID 28377496, 2017). "On the other hand, defects in FECH or UROS do not severely impair heme biosynthesis in the liver but instead result in the onset of erythropoietic protoporphyria (EPP) or congenital erythropoietic porphyria (CEP)." (PMID 26557657, 2015).
glioma (20 papers, 2011 to 2025). A benign or malignant brain and spinal cord tumor that arises from glial cells (astrocytes, oligodendrocytes, ependymal cells). "In vitro analyses using glioma cell lines engineered to express IDH1 mutations demonstrated elevated levels of ferrochelatase (FECH) and heme oxygenase-1 (HO-1), enzymes involved in heme metabolism." (PMID 41008917, 2025). "To find the potential cause of poor PpIX accumulation in SP-defined GSCs, we first assessed the relevance of the FECH gene, encoding an iron-dependent enzyme that converts PpIX to heme, in human glioma malignancies." (PMID 28169355, 2017). "Since gliomas are deficient in ferrochelatase enzyme, accumulation of the fluorophore protoporphyrin IX exhibits strong fluorescence in gliomas compared to surrounding brain tissue under blue light." (PMID 26284196, 2015). "In our study, FECH siRNA significantly enhanced 5-ALA-PDT efficacy in glioma cells caused by marked growth inhibition and abundance of apoptotic cells under unchanged above parameters except for photosensitizer (PpIX) concentration." (PMID 21304523, 2011). "As SDT relies on an enzymatic reaction as opposed to direct DNA modification, including a decreased expression of ferrochelatase in glioma cells, resistance is less likely." (PMID 39904876, 2025). "In many high-grade gliomas, dysregulated porphyrin metabolism and reduced FECH activity result in selective PpIX accumulation." (PMID 41008917, 2025). "The role of DFO in inhibiting glioma cell ferrochelatase is therefore unclear and requires further clarification." (PMID 39201395, 2024). "In contrast, we recently found a significantly increased FECH mRNA expression in WHO grade IV compared to WHO grade II gliomas in a large “The Cancer Genome Atlas” (TCGA) cohort including 424 glioma samples." (PMID 35665365, 2022). "The ablation of FECH in glioma cells by the use of the siRNA approach resulted in increased fluorescence of PpIX, which occurred concomitantly with an increase in the amount of PpIX that accumulated within the cells in response to 5-ALA." (PMID 36059798, 2022). "When compared to normal brain tissues, glioma tissues underwent a considerable reduction in FECH mRNA expression." (PMID 36059798, 2022). "Augmentation of PpIX fluorescence by ferrochelatase inhibition using iron chelators has been demonstrated in vitro in glioma cell cultures." (PMID 32582530, 2020). "Depletion of FECH by small interference RNA enhanced PpIX fluorescence after exposure to 5-ALA concomitant with increased intracellular PpIX accumulation in glioma cells." (PMID 21304523, 2011). "The expression levels of FECH in human normal brain tissues (n=15) and glioma specimens (n=66) were evaluated by QRT–PCR using β-actin mRNA as an internal reference for normalisation." (PMID 21304523, 2011). "The expression levels of FECH mRNA in these three glioma cell lines were significantly different, being highest in G112 and lowest in U87." (PMID 21304523, 2011). "Bright and clear red fluorescence were visualised in glioma cells transfected with FECH siRNA compared with control." (PMID 21304523, 2011). "To overcome these issues, we assessed the expression of ferrochelatase (FECH) gene, which encodes a key enzyme that catalyses the conversion of protoporphyrin IX (PpIX) to heme, in glioma surgical specimens and manipulated FECH in human glioma cell lines." (PMID 21304523, 2011). "In this study, we examined FECH expression and localisation in glioma surgical specimens and the correlation between FECH expression and PpIX accumulation in glioma cell lines." (PMID 21304523, 2011). "Ferrochelatase expression seemed to be reduced in glioma tissues compared with normal brain tissues." (PMID 21304523, 2011). "As we expected, FECH siRNA caused abundant PpIX accumulation and more visible red fluorescence in glioma cells, suggesting that FECH silencing can improve PpIX fluorescence discrimination accuracy." (PMID 21304523, 2011).
glioma (continued). "In addition, higher mRNA levels of the PpIX degrading protein FECH were observed in WHO grade IV gliomas." (PMID 32722247, 2020). "Also, no distinct difference was observed between the expression of FECH in GBMs versus lower grades of gliomas." (PMID 28169355, 2017). "Silencing of FECH caused marked growth inhibition and apoptosis induction by PDT in glioma cells." (PMID 21304523, 2011). "Thus, this study is the first to reveal that FECH has a role in the metabolism of 5-ALA in glioma." (PMID 21304523, 2011). "In glioma cells that had been treated with PDT, suppressing FECH expression resulted in a remarkable attenuation in growth and an enhancement in the process of apoptosis." (PMID 36059798, 2022). "According to our data, we found distinct increases in the 5-ALA metabolizing enzymes CPOX, PPOX, and FECH and decreases in the PpIX exporting transporter ABCG2 on protein level in fluorescing glioma samples." (PMID 35665365, 2022). "For this purpose, we compared the mRNA as well as protein expression of CPOX, PPOX, FECH, and ABCG2 in 19 glioma tissue samples with presence of strong 5-ALA induced fluorescence during surgery to 21 non-fluorescing glioma samples." (PMID 35665365, 2022). "In this sense, we recently observed significant differences in the mRNA expression in 8 of 11 analyzed genes (HMBS, UROD, FECH, PPOX, SLC15A2, ALAD, UROS, and ABCB6) involved in the heme biosynthesis between WHO grade II and IV gliomas." (PMID 33562253, 2021). "Significant differences in mRNA expression included increases of HMBS, UROD, FECH and PPOX as well as decreases of SLC15A2, ALAD, UROS and ABCB6 in WHO IV gliomas." (PMID 32722247, 2020). "Previous studies demonstrated that treatment of glioma cells with N-methyl mesoporphyrin IX (NMP), an inhibitor of ferrochelatase, blocks the activity of CcO." (PMID 25726526, 2015). "An ∼42-kDa single band of FECH was clearly detected in the G112 and SNB19 cell lines, but faintly detected in U87 glioma cells." (PMID 21304523, 2011). "Silencing FECH gene expression significantly increased ALA-PpIX fluorescence in human colon, urothelial, glioma and breast cancer cells and sensitized cells to ALA-PDT whereas overexpression of FECH reduced cell sensitivity to ALA-PDT by decreasing PpIX production." (PMID 26516850, 2015). "Ferrochelatase mRNA expression in G112, SNB19, and U87 glioma cell lines was determined by QRT–PCR." (PMID 21304523, 2011). "The results of this study demonstrate that protein levels of the investigated heme biosynthesis factors do not correlate with mRNA expression in gliomas in most cases (CPOX, PPOX, and FECH)." (PMID 35665365, 2022). "To this end, we compared the mRNA as well as protein expression levels of CPOX, PPOX, FECH and ABCG2 in glioma tissue samples with presence of strong 5-ALA induced fluorescence during surgery to non-fluorescing glioma samples." (PMID 35665365, 2022).